SLC5A6 (solute carrier family 5 member 6)
Description:
Sodium-dependent multivitamin transporter that mediates the electrogenic transport of pantothenate, biotin, lipoate and iodide. Functions as a Na(+)-coupled substrate symporter where the stoichiometry of Na(+):substrate is 2:1, creating an electrochemical Na(+) gradient used as driving force for substrate uptake. Required for biotin and pantothenate uptake in the intestine across the brush border membrane. Plays a role in the maintenance of intestinal mucosa integrity, by providing the gut mucosa with biotin (By similarity). Contributes to the luminal uptake of biotin and pantothenate into the brain across the blood-brain barrier.
Synonyms: hSMVT; SMVT; COMNB; NERIB; SMVTD
Tractability: Antibody: UniProt places it where antibodies can reach, with high confidence; its Gene Ontology location is reachable by antibodies, with high confidence; UniProt predicts a signal peptide or a membrane-spanning region; the Human Protein Atlas places it where antibodies can reach. PROTAC: ubiquitination databases record sites on it; its protein half-life has been measured.
Target class: Transporter
Gene: Protein-coding gene on chromosome 2 (27,199,587 to 27,212,958, reverse strand). Ensembl gene ENSG00000138074.
Subcellular location: Cell membrane; Apical cell membrane
Subcellular location (Human Protein Atlas): Plasma membrane
Pathways (Reactome):
Metabolism: Biotin transport and metabolism; Vitamin B5 (pantothenate) metabolism
Transport of small molecules: Transport of vitamins, nucleosides, and related molecules
Gene Ontology:
Molecular function: biotin transmembrane transporter activity; iodide transmembrane transporter activity; pantothenate transmembrane transporter activity; protein binding; vitamin transmembrane transporter activity; sodium-dependent multivitamin transmembrane transporter activity; monoatomic ion transmembrane transporter activity; pantothenate:sodium symporter activity; transmembrane transporter activity
Biological process: biotin import across plasma membrane; biotin transport; iodide transmembrane transport; pantothenate transmembrane transport; transport across blood-brain barrier; sodium ion transport; biotin metabolic process; sodium ion import across plasma membrane; transmembrane transport
Cellular component: apical plasma membrane; plasma membrane; basolateral plasma membrane; membrane; brush border membrane
Genetic constraint (gnomAD): Loss-of-function variants: 30 observed, 66.8 expected, observed/expected ratio (o/e) 0.45, 90% interval 0.34 to 0.61. The upper end of that interval is the gene's LOEUF score, 0.61, which puts it in group 2 of 6, group 1 being the genes least tolerant of losing a copy. Missense variants: 665 observed, 845.45 expected, observed/expected ratio (o/e) 0.79, 90% interval 0.74 to 0.84. Synonymous variants: 341 observed, 346.33 expected, observed/expected ratio (o/e) 0.98, 90% interval 0.9 to 1.08.
Homologues: Orthologues: chimpanzee SLC5A6 (99% identical), macaque SLC5A6 (95% identical), rabbit SLC5A6 (86% identical), pig SLC5A6 (85% identical), rat Slc5a6 (83% identical), mouse Slc5a6 (83% identical), tropical clawed frog slc5a6 (64% identical), zebrafish slc5a6a (63% identical), zebrafish slc5a6b (57% identical), Drosophila melanogaster CG32669 (34% identical), Drosophila melanogaster CG10444 (34% identical). Paralogues in human: SLC5A8 (42% identical), SLC5A12 (40% identical), SLC5A5 (37% identical), SLC5A11 (21% identical), SLC5A10 (21% identical), SLC5A9 (20% identical), SLC5A2 (20% identical), SLC5A1 (19% identical), SLC5A3 (19% identical), SLC5A4 (19% identical), SLC5A7 (17% identical).
Diseases named in the same sentence as SLC5A6 in open-access papers:
SLC5A6 is named in the same sentence as 34 diseases in open-access papers, as found by Europe PMC text mining. Sharing a sentence is not in itself a finding about the gene and the disease. The quoted sentences say what the papers report.
biotin deficiency (3 papers, 2022 to 2023). "The results showed that SLC5A6 was a Physical Interaction with PCCB and the diseases associated with SLC5A6 include Neurodegeneration, Infantile-Onset, Biotin-Responsive, and Biotin Deficiency." (PMID 36138824, 2022).
colitis (3 papers, 2013 to 2023). Inflammation of the colon. "In earlier studies to explore how biotin levels impact the microbiome and colitis, we generated mice with an intestine-specific conditional knock-out of the biotin transporter (SMVT; Slc5a6)." (PMID 36678135, 2023).
biotinidase deficiency (2 papers, 2019 to 2022). A late-onset form of multiple carboxylase deficiency, an inborn error of biotin metabolism that, if untreated, is characterized by seizures, breathing difficulties, hypotonia, skin rash, alopecia, hearing loss and delayed development. "The exclusion of biotinidase deficiency in all patients support the association of biallelic SLC5A6 variants with motor neuropathies in the current cohort." (PMID 35013551, 2022).
developmental delay (2 papers, 2022 to 2023). "SLC5A6, a sodium-dependent multivitamin transporter, has been associated with neurological disorders such as ataxia, developmental delay, and seizures under abnormal nutritional conditions." (PMID 36980356, 2023). "Compound heterozygous SLC5A6 variants have been reported in individuals with variable multisystemic disorder, including failure to thrive, developmental delay, seizures, cerebral palsy, brain atrophy, gastrointestinal problems, immunodeficiency, and/or osteopenia." (PMID 35013551, 2022).
gastric cancer (2 papers, 2023 to 2025). A primary or metastatic malignant neoplasm involving the stomach. "It was stated that SLC5A6 may potentially be a diagnostic and prognostic biomarker in gastric cancer." (PMID 41465541, 2025).
acute peritonitis (1 paper, 2013). "Two-thirds of the intestinal slc5a6−/− mice died prematurely due to acute peritonitis." (PMID 23725086, 2013).
Encephalopathy (1 paper, 2022). Encephalopathy is a term that means brain disease, damage, or malfunction. "A previously reported patient with biallelic SLC5A6 variants had a severe metabolic crisis with encephalopathy." (PMID 35013551, 2022).
Failure to thrive (1 paper, 2022). Failure to thrive (FTT) refers to a child whose physical growth is substantially below the norm. "Two previously reported patients with biallelic SLC5A6 variants also showed failure to thrive and triple vitamin replacement therapy, likely via a simple diffusion mechanism, had beneficial effects in the three live patients." (PMID 35013551, 2022). "A 3-year-old girl with compound heterozygous SLC5A6 p.(Val141Alafs*34) and p.(Gln622Argfs*51) variants had failure to thrive and delayed motor development in infancy." (PMID 35013551, 2022).
hyperuricemia (1 paper, 2018). An abnormally high level of uric acid. "However, the transcription levels of both SLC17A2 and SLC5A6 were significantly different between the hyperuricemia patients and healthy subjects, suggesting that these two genes potentially affect serum urate levels." (PMID 29497127, 2018).
metabolic syndrome (1 paper, 2018). A cluster of metabolic risk factors for CARDIOVASCULAR DISEASES and TYPE 2 DIABETES MELLITUS. "A notable proportion of genes within the enriched pathways in liver are related to the biological clock, including Wee1, Per2 and Slc5a6, each previously reported to be associated with the development of metabolic syndrome." (PMID 30619467, 2018).
sensorimotor peripheral neuropathy (1 paper, 2022). "One previously reported patient with biallelic SLC5A6 variants developed mixed axonal and demyelinating sensorimotor peripheral neuropathy from 3 years of age on that resolved post vitamin treatment." (PMID 35013551, 2022).
tumor (4 papers, 2020 to 2025). "We quantified the mRNA expression of SLC5A6 in normal endothelial, fibroblast, epithelial, and epidermal cells as well as in the common tumor cell lines HeLa, HEK293T, and U937." (PMID 41402538, 2025). "Notably, we show that SLC5A6 over-expression alone can induce increased cell growth and a shift toward biosynthesis, whereas conversely, dietary restriction of pantothenic acid leads to a reversal of many MYC-mediated metabolic changes and results in hampered tumor growth." (PMID 37946084, 2023).
genetic disorder (2 papers, 2019 to 2024). "Recognition of the genetic disorder caused by SLC5A6 mutations is essential for early diagnosis and to facilitate timely intervention by triple vitamin (biotin, pantothenate, and lipoate) replacement therapy." (PMID 31754459, 2019).
infection (2 papers, 2015 to 2025). The state of being infected such as from the introduction of a foreign agent such as serum, vaccine, antigenic substance or organism. "In addition to immunity, genes associated with metabolism (e.g. SLC5A6, SLC2A5, UGT2A3, and PDE6C) as well as membrane proteins, like TM4SF4, were also detected with a significantly higher expression level in CE infection sheep at four hour post infection, when compared with healthy controls." (PMID 26252489, 2015).
adenocarcinoma (1 paper, 2025). A common cancer characterized by the presence of malignant glandular cells. "Regarding AKRB7A2, SLC5A6, and SLC29A2, for the first time, a significant role in CRC adenocarcinoma development as well as in a healthy colon is presented." (PMID 41465541, 2025).
SLC5A6 also shares sentences with these, for which no sentence is quoted: cancer (8 papers); Ataxia (1); Brain atrophy (1); breast carcinoma (1); cerebral palsy (1); dementia (1); glioma (1); head and neck cancer (1); hepatocellular carcinoma (1); Immunodeficiency (1); lung adenocarcinoma (1); lung carcinoma (1); metabolic disorder (1); Neurodegeneration (1); neurological disorders (1); optic atrophy (1); Osteopenia (1); peripheral neuropathies (1); Seizure (1).